HOXA5 (homeobox A5)
Diseases named in the same sentence as HOXA5 in open-access papers (continued):
Sharing a sentence is not in itself a finding about the gene and the disease.
glioma (continued). "We constructed a risk model using HOXA5, PTPN2, WT1, HOXD10, POSTN, ADAMDEC1 and MYBPH expression data from a cohort of patients in TCGA, and found that it had significant prognostic value for ATRX-wt glioma patients." (PMID 37812190, 2023). "Kaplan-Meier survival curves were generated based on median values of HOXA5 expression in gliomas." (PMID 34485110, 2021). "HOXA5 was also highly expressed in primary glioma (P <0.001, respectively), whereas the analysis for first-course treatment outcome showed that progressive disease was correlated with higher expression of HOXA5 (P <0.001, respectively)." (PMID 34485110, 2021). "Furthermore, HOXA5 was upregulated in the 1p19q codeletion in pan-glioma analysis in both TCGA and CGGA data sets (P <0.001, respectively)." (PMID 34485110, 2021). "Importantly, we found that CD133 expression in glioma was highly correlated with the expression of HOX gene stem cell factors (HOXA5, HOXA7, HOXA10, HOXC4 and HOXC6)." (PMID 28055976, 2017). "Additionally, HOXA5 was upregulated in the unmethylated gliomas in TCGA data set (P <0.001)." (PMID 34485110, 2021). "Hox genes (HOXA2, HOXA5, and HOXA7) can regulate several hallmarks of cancer in malignant glial tumors." (PMID 37397378, 2023). "The T cell depletion-related prognostic model was developed based on seven prognostic genes (HSPB1, HOXD10, HOXA5, SEC61G, H19, ANXA2P2, HOXC10) in glioma." (PMID 36531217, 2022). "As the IDH mutation exerted great influence on the methylation of the whole genome, we separately analyzed the relationship between HOXA5 and methylation status for IDH‐wild and IDH‐mutant gliomas." (PMID 34485110, 2021). "Therefore, HOXA5 widely affected tumor progression, but its role in glioma is still unknown." (PMID 34485110, 2021). "In the present study, we found that HOXA5, HOXA7, HOXA10, HOXC4 and HOXC6 are prognostic markers in glioma patients." (PMID 28055976, 2017). "HOXA5 methylation correlated with prognosis in BLCA, glioma, CESC, and HNSC." (PMID 41209012, 2025). "In conclusion, our study revealed that an immune signature based on HOXA5, PTPN2, WT1, HOXD10, POSTN, ADAMDEC1 and MYBPH expression effectively predicted the prognosis of ATRX-wt glioma patients, and demonstrated that immunotherapy was effective for low-risk patients." (PMID 37812190, 2023). "A receiver operating characteristic curve analysis indicated that HOXA5, PTPN2, WT1, HOXD10, POSTN, ADAMDEC1 and MYBPH had significant prognostic value for the survival of ATRX-wt glioma patients (AUC = 0.84, 0.81, 0.79, 0.91, 0.80, 0.79 and 0.85, respectively)." (PMID 37812190, 2023). "Patients without 1p19q codeletion also had the highest expression of HOXA5 in pan-glioma analysis and LGG alone in TCGA microarray data set (P <0.001, respectively)." (PMID 34485110, 2021). "We also evaluated the expression levels of HOXA5 in different age groups in pan-glioma analysis in TCGA and CGGA data sets, and in GBM patients in TCGA microarray data set, where patients older than 45 years have higher expression of HOXA5 (P <0.001, respectively)." (PMID 34485110, 2021). "High HOXA5 expression samples contain unfavorable clinical features of glioma, including IDH wild type, un-methylated MGMT status, non-codeletion 1p19q status, malignant molecular subtype." (PMID 34485110, 2021).
glioma (continued). "Receiver operating characteristic (ROC) curve further indicated that HOXA5 might serve as a predictor for CL and MES subtypes in pan-gliomas analysis (AUC value = 0.898, P <0.001)." (PMID 34485110, 2021). "In addition, in pan-glioma analysis in TCGA microarray data set, HOXA5 also had the highest expression in patients without IDH mutation (P <0.001, respectively), in patients without radiotherapy (P <0.001, respectively)." (PMID 34485110, 2021). "Analysis of individual loci in glioma samples using strand‐oriented RNA‐seq data supported the hypothesis that transcription can initiate from these H3K4me3‐marked TSS, embedded in methylated areas (see, for instance, HOXA5 and HOXA10)." (PMID 33720519, 2021).
acute myeloid leukemia (9 papers, 2012 to 2025). Acute myeloid leukemia (AML) is a group of neoplasms arising from precursor cells committed to the myeloid cell-line differentiation. "HOXA5 is upregulated in oral squamous cell carcinoma and its loss inhibits proliferation and cell tumorigenesis in esophageal squamous cell cancer and acute myeloid leukemia cells, suggesting that HOXA5 may act as an oncoprotein in these cells." (PMID 31159758, 2019). "In acute myeloid leukemia (AML), aberrant HOXA5 expression is associated with treatment response and overall survival." (PMID 40805172, 2025). "For instance, lncRNA HOTAIR was shown to recruit DNMT3B to increase HOXA5 promoter methylation and silence its expression in acute myeloid leukemia (AML)." (PMID 36533073, 2022). "Additionally, in acute myeloid leukemia (AML), WBP5 overexpression has been associated with poor prognosis, correlating with increased expression of HOX gene cluster (HOXA5, HOXA7, HOXA9, and HOXA10), MEIS1, and FOXC1." (PMID 40002180, 2025). "In addition, the hypermethylation of HOXA5, together with five other genes (ABCA3, COX7A1, SLIT3, SOX17, SPARCL1), has been linked to lung adenocarcinoma development, while HOXA4 and HOXA5 present altered methylation profiles in a significant number of patients with acute myeloid leukemia." (PMID 32635388, 2020). "For instance, loss of HOXA5 in breast cancer, over-expression of HOXA10 in acute myeloid leukemia (AML), gene mutations of HOXD4 in renal and colon cancer and overexpression of HOXC4 in human bladder cancer have been reported." (PMID 22768238, 2012).
ovarian carcinoma (9 papers, 2009 to 2025). A malignant neoplasm originating from the surface ovarian epithelium. "One of the PRC targets, the HOXA5 gene, seems to play a significant role in ovarian biology and may be involved in ovarian cancer predisposition, since the loss of HOXA5 function leads to the formation of ovarian epithelial cysts in older females." (PMID 39456618, 2024). "In ovarian cancer HOXA5+ malignant cells, the IGFBP pathway was a key mediator, influencer, sender, and receiver." (PMID 41209012, 2025). "The ovarian epithelial inclusion cysts in Hoxa5−/− mice also express the ovarian cancer markers PAX8 and WT1 suggesting that they constitute preneoplastic lesions and that the loss of Hoxa5 function confers ovarian cancer predisposition." (PMID 29615582, 2016).
glioblastoma (7 papers, 2015 to 2025). The most malignant astrocytic tumor (WHO grade IV). "By catalyzing H3K27me3, EZH2 represses a series of tumor suppressor genes associated with the tumorigenic properties of glioblastoma, including CDKN1B, RUNX3, and HOXA5." (PMID 35927718, 2022). "A recent study showed that another gene located on chromosome 7, Homeobox A5 (HOXA5), is overexpressed in a part of glioblastomas and promotes tumor cell proliferation and radioresistance." (PMID 30279357, 2018). "Besides, previous study confirmed that HOXA5 can affect glioblastoma cells sensitivity to radiation therapy." (PMID 34485110, 2021). "HOXA5 gene overexpression promotes an aggressive phenotype in glioblastoma." (PMID 30279357, 2018). "Also, we used tool ‘GEO profiles’ of NCBI to search the expression of two homeobox genes (HOXA5 and HOXA10) and two cadherin genes (PCDHA1 and PCDHB13) in different grades of the glioblastoma." (PMID 27160082, 2016). "in 2021 found that the prognosis of glioblastoma (GBM) can be determined by seven differentially expressed genes (DEGs) 47, namely CLEC5A, HOXC6, HOXA5, CCL2, GPRASP1, BSCL2, and PTX3." (PMID 39132508, 2024).
hepatocellular carcinoma (7 papers, 2020 to 2025). A malignant tumor that arises from hepatocytes. "In addition, its up-regulation in hepatocellular carcinoma leads to a decrease in the expression of HOXA5, which in turn promotes tumor growth and angiogenesis, is associated with a poor prognosis." (PMID 34567057, 2021). "Studies have shown that HOXA5 acts as a tumor suppressor to inhibits tumor growth and recurrence by regulating the PI3K/AKT/mTOR signaling pathway in hepatocellular carcinoma." (PMID 38702814, 2024).
lung adenocarcinoma (7 papers, 2015 to 2025). A carcinoma that arises from the lung and is characterized by the presence of malignant glandular epithelial cells. "The objective of this study was to investigate the biological functions of HOXA5 in human lung adenocarcinoma cells and its association with survival in NSCLC patients." (PMID 25875824, 2015). "Oligonucleotide microarrays and an invasion/metastasis lung adenocarcinoma cell line model were used to determine the correlation between HOXA5 expression and cancer cell invasion ability." (PMID 25875824, 2015). "The data presented here show that the overexpression of HOXA5 could suppress lung adenocarcinoma cell migration and invasion in vitro and in vivo." (PMID 25875824, 2015). "The knockdown of HOXA5 rescued the invasive capabilities of lung adenocarcinoma cells." (PMID 25875824, 2015). "All these results suggest that the calcium/InsP3R/CaMKII axis may be involved in lung adenocarcinoma cell migration and that HOXA5 expression can transcriptionally reduce the expression of these genes and inhibit this signalling pathway." (PMID 25875824, 2015).
Insulin resistance (6 papers, 2019 to 2025). Increased resistance towards insulin, that is, diminished effectiveness of insulin in reducing blood glucose levels. "While studies on Hox gene expression in adipose tissue are limited, some investigations involving humans and mice suggest that Hox genes, such as HoxA5, regulate inflammation, energy metabolism, thermogenesis and insulin resistance." (PMID 40501971, 2025). "The genes HOXA5 and ST18 have been implicated in biological processes relevant to insulin resistance." (PMID 35836279, 2022). "Differential methylation of our top DMP, cg14013695 (HOXA5) seems to play a role in the pathogenesis of insulin resistance across populations." (PMID 35836279, 2022). "This evidence clearly points to a link between DNA methylation in HOXA5 and the pathogenesis of insulin resistance." (PMID 35836279, 2022). "We found that cg14013695 (TSS1500 of HOXA5) was previously reported in an EWAS on insulin resistance among Mexican Americans (Beta = − 0.174, p = 1.49E − 7, FDR = 0.056)." (PMID 35836279, 2022). "Among these DMRs, SREBF1, HOXA5, CPT1A, LPIN1, and PHGDH have established roles in adipose tissue biology and insulin resistance." (PMID 33243154, 2020). "In the GWAS catalog, we found out that genetic variants annotated to HOXA5, OSR1 and ST18 were not independently related to insulin resistance traits." (PMID 35836279, 2022).
osteosarcoma (6 papers, 2020 to 2024). A usually aggressive malignant bone-forming mesenchymal neoplasm, predominantly affecting adolescents and young adults. "In osteosarcoma, elevated expression of miR-196a predicts poor prognosis and has been shown to promote cell migration, invasion and the epithelial–mesenchymal transition by targeting HOXA5." (PMID 35887151, 2022). "Similarly, miR-26a-5p, which can promote proliferation and migration of osteosarcoma by targeting HOXA5 acting as a tumor oncogene for osteosarcoma, could be exploited in the future as part of specific therapies for this disease." (PMID 39519267, 2024). "A study on osteosarcoma reported that the expression level of miR-196a in osteosarcoma cells was significantly higher than that in normal tissues, and this molecule ultimately promoted the metastasis of tumor cells and extracellular matrix transformation by targeting the 3′-UTR of HOXA5 mRNA." (PMID 36979489, 2023).
liposarcoma (5 papers, 2015 to 2025). A usually painless malignant tumor that arises from adipose tissue. "By inhibiting miR-26a-2 expression and concurrent HOXA5-overexpression, the susceptibility of liposarcoma cells to p-53 independent apoptotic stimuli, significantly increases." (PMID 28895916, 2017). "By inhibiting HOXA5 in liposarcoma cells, miR-26a-2 halted apoptosis, leading to uncontrolled cellular growth." (PMID 39736850, 2025). "Homeobox protein A5 (HOXA5), which is downregulated in liposarcoma, constitutes another target of miR-26a-2." (PMID 28895916, 2017). "Two years later, the same group of researchers discovered that miR-26a-2 was overexpressed (p < 0.05) by about 10-fold in liposarcoma cell lines, and it could repress the expression homeobox protein 5 (HOXA5) in vitro." (PMID 39736850, 2025).
prostate carcinoma (5 papers, 2019 to 2025). A carcinoma that arises from epithelial cells of the prostate gland. "Additionally, TRAF7 overexpression has also been implicated in the pathophysiology of prostate cancer through its effect on Homeobox A5 (HOXA5)." (PMID 41372821, 2025). "Homeobox A5 (HOXA5), a homeodomain transcription factor, is considered a tumor suppressor in cancer progression; however, its function in prostate cancer (PCa) remains unclear." (PMID 37845209, 2023). "HOXA13, HOXA1, HOXA5, HOXA6, HOXA7, HOXA9, and HOXA10 are involved in prostate cancer, and they form a DNA loop with a locus that induces prostate cancer and regulates gene transcription." (PMID 37590265, 2023).
squamous cell carcinoma (5 papers, 2015 to 2021). A carcinoma arising from squamous epithelial cells. "However, another report indicated that HOXA5 expression was higher in squamous cell carcinoma and adenocarcinoma tissues than in non-cancerous tissues." (PMID 25875824, 2015).
asthma (4 papers, 2020 to 2025). "Further, in a study using Hox5 compound null alleles (Hoxa5+ ⁣/−; Hoxb5–/–; Hoxc5+ ⁣/−), mice present with an increased Th2 cells response and exacerbated lung tissue pathology in asthma models." (PMID 34901011, 2021). "Gene expression analysis using data in blood from 832 children and lung from 424 adults showed associations between identified DMCs using maternal asthma and expression of several genes, including HLA genes and HOXA5, previously implicated in asthma or lung function." (PMID 40349045, 2025). "Altered expression of HLA genes has previously been linked to asthma and allergy while perturbed expression of HOXA5 has been associated with impaired lung function in children and in adults highlighting the importance of future studies investigating their role in asthma pathogenesis." (PMID 40349045, 2025). "We identified differential methylation in regions related to parental asthma involving the HOXA5 and HLA genes." (PMID 40349045, 2025). "We also identified differential methylation in regions related to parental asthma involving the HOXA5 and HLA genes." (PMID 40349045, 2025). "A previous study has shown the involvement of HOXA5 in predicting COPD and asthma in adulthood based on cord blood DNA methylation measured in newborns." (PMID 41421321, 2025). "HOXA5 is also the target of CHEMBL4224852, a lysine demethylase, which may implicate epigenetic regulation in asthma development." (PMID 40349045, 2025). "For the remaining genes (airway fibroblasts: HOOK2 and HOXA7; parenchymal fibroblasts: HOXA5, HOXA6, HOXA-AS3, RB1 and NR2F1-AS1), there was no differential gene expression between donors with and without asthma." (PMID 33008450, 2020).
atherosclerosis (4 papers, 2020 to 2025). A disease characterized by the build-up of fatty material and calcium deposition in the arterial wall resulting in partial or complete occlusion of the arterial lumen. "HOXA5 safeguards against atherosclerosis via peroxisome proliferator-activated receptor gamma (PPARγ), whereas HOXB9 exacerbates inflammation through bone morphogenetic protein 4-tumor necrosis factor (BMP4-TNF)." (PMID 41181801, 2025). "Statin treatment significantly enhanced the synthesis of HOXA5, thereby reinforcing their role in modulating pluripotency disarray during the development of atherosclerosis." (PMID 38610757, 2024).
Sepsis (4 papers, 2022 to 2025). Sepsis is defined as life-threatening organ dysfunction caused by a dysregulated host response to infection. "In a distinct pathway, SIRT5 inhibits ferroptosis and ameliorates sepsis-induced lung injury by desuccinylating HOXA5 to upregulate FSP1 expression." (PMID 41480383, 2025). "This study aimed to explore the role and potential mechanism of HOXA5 desuccinylation in the regulation of ferroptosis in sepsis‐induced lung injury." (PMID 39713961, 2025). "In a mouse model of lipopolysaccharide-induced sepsis, HOXA5 overexpression alleviated the clinical manifestations of sepsis." (PMID 40959280, 2025). "Accordingly, we hypothesized that SIRT5 regulates HOXA5 desuccinylation in sepsis‐induced lung injury." (PMID 39713961, 2025). "Thus, SIRT5 overexpression increased HOXA5 desuccinylation, thereby inhibiting ferroptosis in sepsis‐induced lung injury." (PMID 39713961, 2025). "Homeobox A5 (HOXA5) is involved in the regulation of AKI occurrence and development in sepsis." (PMID 40959280, 2025). "Therefore, HOXA5 may regulate FSP1‐mediated ferroptosis and participate in sepsis‐induced lung injury." (PMID 39713961, 2025).
acute lymphoblastic leukemia (3 papers, 2010 to 2024). Leukemia with an acute onset, characterized by the presence of lymphoblasts in the bone marrow and the peripheral blood. "Physcion blocks cell cycle and induces apoptosis in human B cell precursor acute lymphoblastic leukemia cells by downregulating HOXA5." (PMID 31827437, 2019). "MEIS1 and HOXA5 were enriched in Thy1 cells and may maintain the stemness of T precursor cells as the upregulation of them were reported in acute lymphocytic leukemias." (PMID 38318192, 2024). "Another group of T-cell acute lymphoblastic leukemia (T-ALL)-associated oncogenes are homeobox genes and includes members of the NK-like family, TLX1/HOX11, TLX3/HOX11L2 and NKX2-5/CSX, and of the clustered homeobox genes, HOXA5, HOXA9, HOXA10 and HOXA11." (PMID 20565746, 2010).